FABP4 (fatty acid binding protein 4)
Diseases named in the same sentence as FABP4 in open-access papers (continued):
Sharing a sentence is not in itself a finding about the gene and the disease.
tumor (continued). "We reveal that exposure to lipids supplied by marrow adipocytes induces expression of lipid chaperone FABP4, pro-inflammatory interleukin IL-1β, and oxidative stress protein HMOX-1 in metastatic tumor cells and stimulates their growth and invasiveness." (PMID 24240026, 2013). "In cancers, where a sustained energy supply and lipogenic signaling are essential for tumor growth and survival, DHA-induced restriction of energy influx, together with the downregulation of Pparγ, Fabp4, Fasn, Gpr120, and Slc2a4, disrupts key pro-tumorigenic pathways." (PMID 41373668, 2025). "In the PPAR signaling pathway, the upregulation of PPARγ and its target gene FABP4, along with the significant downregulation of lipid synthesis enzyme SCD, reveals that EA-2 may remodel tumor cell lipid metabolism by activating the PPARγ pathway." (PMID 40906079, 2025). "To further elucidate the role of the systemic inflammatory response in HF-induced TRAMP tumor progression mediated by FABP4, we performed a comprehensive cytokine array using sera derived from the 24-week-old FABP4−/− TRAMP and TRAMP mice fed the HF (3 mice per group)." (PMID 41226657, 2025). "For example, FABP4+ LAMs release pro-inflammatory factors through lipolysis to suppress T cell function, and FABP6+ tumor cells downregulate MHC-I molecules to reduce T cell recognition, demonstrating the central role of FABPs in metabolic crosstalk between tumors and immune cells." (PMID 40717587, 2025). "Furthermore, activation of the FABP4/UCP2 axis is prominently observed in CAAs, where it regulates complex functions in tumor progression and drug responses." (PMID 39823981, 2025). "FABP4 is downregulated in HCC tissues and functions as a tumour suppressor." (PMID 41149452, 2025). "Increasing research indicates that adipokines (such as leptin, resistin, visfatin, etc.)and inflammatory factors (such as IL-1β, IL-6, chemokines, FABP4, etc.)secreted by BMA can also regulate angiogenesis, indirectly facilitating the progression of tumor bone metastasis." (PMID 38571500, 2024). "In this dataset, all the 7-gene candidates exhibited a significant increase of mRNA expression in the metastasis group relative to localised tumours, with RUVBL1 exhibiting near statistical significance (U2AF2 P = 0.0106, RUVBL1 P = 0.051, HDGF P < 0.0001, FABP4 P = 0.0005, and STMN1 P = 0.032)." (PMID 39402324, 2024). "The FABP4/LA-induced tumor migration effect was not due to tumor proliferation as Ki67 expression was similar among different FA-treated groups." (PMID 39513934, 2024). "Fatty acid binding protein 4 (FABP4), a lipid chaperone that facilitates lipid distribution and response in cells, is highly expressed in NB macrophages compared to other cell types of the TME, leading to tumor progression." (PMID 38397187, 2024). "To compare the efficacy of the V9 antibody, we compared E0771 tumor growth in WT mice treated with or without V9 and in FABP4−/− mice." (PMID 39054536, 2024). "Evidence for the relationship between FABP4 and LNM in CRC is limited, but it is closely related to tumor progression, and it is believed that the relationship between FABP4 and LNM will become clearer in the future with the corroboration of more clinical data." (PMID 39035744, 2024). "CD36, FABP4, and ANGPTL4 were readily detectable in tumor cells by immunostaining." (PMID 39456610, 2024). "The transfer of FAs from the adipocytes to the tumor cells is realized by CD36 and FABP4." (PMID 39085485, 2024). "It is possible that tumor resection―but not L-carnitine administration―reduces the serum FABP4 levels." (PMID 39458176, 2024). "Multiplex fluorescent immunohistochemistry (mIHC) of FABP4, C1q, and CD68 (a common surface marker of macrophages) was performed on paraffin-embedded tumor tissues, lymph nodes, distal normal lung tissues of patients with NSCLC, and the same results were obtained." (PMID 39353883, 2024).
tumor (continued). "In our study, the level of FABP4 was not different between HBV-HCC tumor and adjacent tissues (P > 0.05)." (PMID 37950277, 2023). "Furthermore, the highly expressed DEGs of fibroblasts in LNM included immune-related genes (CCL21, CCL19, CCL2, and MYC), metabolism-related genes (STEAP4, FABP4, DPT, and APOE), and genes related to tumor proliferation and progression (RGS, CCN, and MYC)." (PMID 37221625, 2023). "The intracellular expression of FABP4 in macrophages downregulates miR-29b via enhanced activation of NF-κB, which negatively regulates the IL-6/STAT3 signaling pathway and leads to subsequent tumor colony formation." (PMID 36060264, 2022). "Furthermore, metastasizing OC cells have been shown to upregulate expression of the lipid chaperone protein fatty acid binding protein 4 (FABP4), particularly in cells at the adipocyte-tumor interface and FA receptor, CD36." (PMID 36266675, 2022). "The sub‐clustering of ECs revealed six subtypes, including extra‐alveolar capillary EC (cEC) (FCN3+EDN1+PLVAP+), alveolar cEC (HPGD+EDNRB+IL1RL1+), arterial EC(GJA5+FBLN5+DKK2), lymphatic EC (CCL21+TFF3+FABP4), INSR+ tumour EC (INSRhiHSPG2+PLVAP+), and ACKR1+ tumour EC (ACKR1+SELP+IL1R1+)." (PMID 35184398, 2022). "Interestingly, APOA1, FASN, FABP4, and LPL were oppositely dysregulated in liver and lung metastasis compared to the primary CRC tumour, whereas AGPAT1 was found to be significantly upregulated in lung metastasis." (PMID 35957902, 2022). "Moreover, a previous study showed that FABP4 in endothelial cells is induced by the NOTCH1 signaling pathway, which is involved in the resistance mechanism of antiangiogenic tumor therapy." (PMID 36264920, 2022). "Low expression of FABP4 in tumor tissues (p < 0.05) was validated in five datasets, the lower expression of PLXNB3, INHBB and NKAIN4 in tumor tissues was verified in three datasets (p < 0.05), and the decreased expression of HOXC9 and was validated in one dataset, respectively (p < 0.05)." (PMID 35721480, 2022). "FABP4 and FABP5 have the capacity to regulate transcription and may regulate tumor progression through both FA metabolism and/or the modulation of gene expression." (PMID 35721518, 2022). "Overall, these results suggest that FABP4 functions as a strong suppressor of GC metastasis and does not promote tumour growth." (PMID 35198079, 2022). "Exogenous FABP4 can also activate PI3K/Akt pathway independent of fatty acid trafficking in prostate cancer to enhance tumor growth." (PMID 35899119, 2022). "However, tumor cells in tumor 3 expressed S100A7, FABP4, and KRT14, and GO analysis showed that complement activation, epithelial cell differentiation, and negative regulation of growth were highly enriched." (PMID 36569924, 2022). "FABP4 upregulation leads to the activation of the IL-6–STAT3–ALDH1 signalling pathway and an increase in levels of STAT3-activating cytokines, which enhances the stemness of tumour." (PMID 35899119, 2022). "Interestingly, PD-L1 blockade decreases FABP4 and FABP5 expression in tumor cells while upregulating expression of these molecules in TRM cells, promoting TRM cell survival and their antitumor response." (PMID 33922441, 2021). "Compared with patients without LNM, FABP4 expression was increased in tumour tissues in patients with LNM." (PMID 34702269, 2021). "Importantly, in vivo tests showed that LPL, FABP4, and CPT1-related inhibitors delayed tumor growth in STAM mice." (PMID 34803493, 2021). "In this study, the results of tumor spheroid culture and colony formation in vitro showed that small-molecule inhibitors of the LPL/FABP4/CPT1 axis, including Orlistat, BMS309403 and Etomoxir, could inhibit the activity of LCSCs." (PMID 34803493, 2021).
tumor (continued). "We also observed the upregulation of carnitine palmitoyltransferase-1 (CPT1) (662.85-fold of KrasWT CRC tumor), fatty acid binding protein 4 (FABP4) (7.87-fold of KrasWT CRC tumor), and SCD1 (5.1-fold of KrasWT CRC tumor) in KrasG12D CRC tumors (n = 4) compared with KrasWT CRC tumors." (PMID 32131398, 2020). "The fact that basal-TNBC and CL-TNBC tumours had similar expression levels of MYC yet very different expression levels of CD36, LPL, PDK4 and FABP4 suggested that there are likely other factors, besides MYC, that direct activation of FAO and lipid metabolism in CL-TNBC." (PMID 31942031, 2020). "We hypothesized that FABP4 and FABP5 are critical nodes for EET-driven TNBC oncogenic signaling because these lipid chaperone proteins are upregulated in metastatic TNBC tumor specimens overexpressing CYP epoxygenases (CYP2C19)." (PMID 31941087, 2020). "On the basis of our in vivo and in vitro co-culture and EET-supplementation experiments, we hypothesized that inhibiting FABP4 and FABP5 is critical in attenuating EET-driven TNBC tumor growth, relapse, and metastasis." (PMID 31941087, 2020). "Our investigations identified three major invasiveness biomarkers not documented so far in integrative molecular studies characterizing MM, common to the three tumor sources, CAPG, FABP4, and LAMB2, and an additional set of candidate biomarkers shared by rat and patient tumors." (PMID 32867073, 2020). "Besides, it was also demonstrated that the expression level of both FABP4 and FABP5 was downregulated by treatment with berberine in tumor tissues of MGC803 xenografts." (PMID 32328135, 2020). "In the present study, FABP4 expression was significantly decreased in HCC from patients treated with metformin, with a lack of FABP4 staining in tumor endothelial cells." (PMID 30575815, 2019). "This may explain why the serum levels of FABP4 and FABP6 in CRC patients cannot be completely reversed after surgical removal of tumor tissue." (PMID 31651326, 2019). "Interestingly, in this study, immunohistochemistry and western blot analysis showed that FABP4 and FABP6 were mainly expressed in the cells from tumor tissues, and only a small amount distributed in adjacent tissues." (PMID 31651326, 2019). "Thus, FABP1 has been found to increase tumor angiogenesis in hepatocarcinoma by upregulation of VEGF, and FABP4 was shown to enhance cancer aggressiveness in different tumor entities such as myeloid leukemia, prostate and breast cancer." (PMID 31143113, 2019). "Furthermore, we found that FABP4 is low‐expression in human HCC tissues, and the expression level was significantly related to increased tumor sizes and poor prognostic." (PMID 29733540, 2018). "We revealed that FABP4 was significantly low‐expression in HCC tissues compared to the corresponding tissue adjacent at both mRNA and protein level, and the expression level was correlated with tumor size and PVTT." (PMID 29733540, 2018). "These authors demonstrated that FABP4 expression was up-regulated in 17 of 21 pTa samples with progression and down-regulated in 21 of 24 pTa tumours without progression." (PMID 30526555, 2018). "The first one, FABP4, which belongs to a family of intracellular lipid chaperones coordinating the distribution and function of lipids within cells, has been identified as a protective factor to strengthen IFN responses against tumor growth." (PMID 29662647, 2018). "Novel adipocytokines (apelin, endotrophin, Fatty acid binding protein 4 (FABP4), lipocalin 2, omentin-1, visfatin, chemerin, angiopoietin protein 2 (ANGPTL2), and osteopontin) have been identified in various tumor types, enriching the list of potential carcinogenic factors." (PMID 29064461, 2017). "Interestingly, the HFD consumption significantly stimulated adipocyte infiltration in the tumor tissue, and the effect was abrogated by the administration of BMS309403, a FABP4 specific inhibitor." (PMID 29340091, 2017).
tumor (continued). "In high-grade carcinomas, FABP4 was specifically expressed in stroma-rich regions, whereas vessels directly adjacent to tumour cells did not express FABP4." (PMID 27568980, 2017). "Although the contribution of circulating FABP4 from adipocytes to PCa cells and the tumor microenvironment is not clear from our study, our animal study with HFD suggests they are involved." (PMID 29340091, 2017). "To determine whether a similar correlation exists in vivo, we compared Fabp4 and Cd36 levels in TAMs isolated from MMTV-PyMT tumor-bearing mice with peritoneal macrophages isolated from the same mice." (PMID 28974683, 2017). "A recent study reported that FABP4 (A-FABP) plays an important role in regulating the function of VEGF function and promoting proliferation of HUVEC cells; however, the link between L-FABP and tumor malignancy is still unclear." (PMID 26919097, 2016). "When comparing expressions of lipid metabolism—related proteins among molecular subtypes, the expression of PLIN1 (p < 0.001), FABP4 (p = 0.029), CPT-1A (p = 0.001), ACOX-1 (p < 0.001), and FASN (p < 0.001) differed significantly among the different tumor subtypes." (PMID 25751270, 2015). "In this study, we confirmed by immunohistochemical and western blotting analyses that FABP4 was indeed only expressed in tumor stroma and not in tumor cells." (PMID 24732569, 2014). "The coupling of energy metabolism between metastatic cancer cells and their surrounding adipocytes was found to be dependent on the function of fatty acid binding protein 4 (FABP4), expression of which is upregulated in omental metastases compared with the primary tumour." (PMID 24203995, 2013). "This suggests a potential link between FABP4-driven fatty acid uptake and VEGF expression by tumor cells that may be a contributing mechanism to tumor progression in bone that needs further investigation." (PMID 24240026, 2013). "To determine if FABP4, IL-1β, and HMOX-1 are involved in tumor cell adaptation to adipocyte-derived factors, we cultured PC3 cells in media containing gradually increasing amounts of Adipo CM (gradient of 5-25% over multiple passages) and then maintained them long-term in 25% Adipo CM." (PMID 24240026, 2013). "FABP4 overexpression is a tumor-promoting molecule in most cancer types, suggesting that NSC3852 may inhibit histone deacetylation and promote fatty acid transportation via FABP2 and/or FABP4." (PMID 39859448, 2025). "Fatty acid binding protein 4 (FABP4) and glycerol-3-phosphate dehydrogenase 1 (GPD1) separate SR cells from those in other organs through principal component 2, likely due to tissue-specific differences in cellular proteomes, function, and interactions between SR cells and their tumor environment." (PMID 39910169, 2025). "While the IRS for FABP4 was comparable between the normal and overweight/obese group (8.80 versus 9.07), the IRS for ANGTPL4 (6.00 versus 9.80; p = 0.026) and CD36 (2.15 versus 2.60; p = 0.041) were both significantly higher in marginal tumor cells in the overweight/obese group." (PMID 39456610, 2024). "Consistent with the increased secretion of FFAs from beige adipocytes in the tumor microenvironment (TME), cells incubated with adipocyte CM pretreated with MIIP+/− cancer cell CM exhibited higher expression levels of FFA transporters, CD36 and FABP4, compared to cells treated with WT (MIIP+/+) CM." (PMID 38245780, 2024). "Thus, we investigated whether tumor cell expression at the invasive front of the proteins CD36, FABP4, and ANGPTL4, which are involved in the release, cellular uptake, and transport of fatty acids differs between normal and overweight/obese TNBC patients." (PMID 39456610, 2024). "Of note, compared to lipid-processing macrophages, most epithelial-cell-derived cancer cells do not express FABP4, thus FABP4 may serve as a functional marker for lipophilic pro-tumor TAMs." (PMID 39513934, 2024).
tumor (continued). "However, while the increased expression of FABP4 was statistically significant between metastasis and benign tissues adjacent to the tumour (P = 0.0004), this difference was not statistically significant between the metastasis and the normal group (P = 0.088)." (PMID 39402324, 2024). "Endothelial FABP4 may play a role in blood vessel growth, as absence of FABP4 in endothelial cells reduces proliferation and tumor angiogenesis." (PMID 37279064, 2023). "In addition, FABP4 secreted by CAA actively transports FA to tumor cells and the elevated expression of the FA transport proteins such as CD36 and FABP5, leading to an amplified transport of FA to tumor cells and boosting their proliferation." (PMID 36551752, 2022). "Notably, tumors from BC patients, who were treated with metformin prior to tumor removal, contained 3 to 4-fold more FABP4+ LIPEC vessels than tumors from BC patients (diabetic or not), who did not receive this treatment." (PMID 36127427, 2022). "Nur77, a tumor suppressor, inhibits breast cancer cells from uptaking exogenous fatty acids and blocks the accumulation of fatty acids in the tumor metabolic microenvironment by inhibiting the transcription of the transmembrane protein CD36 and the cytoplasmic fatty acid-binding protein FABP4." (PMID 36611922, 2022). "However, even if FABP4 is detected both in OvCA cells and CAAs, systemic treatments targeting tumor and host FABP4 are not more effective in decreasing metastatic nodules than host FABP4 knock-down, highlighting the prominent role of FABP4 in TME." (PMID 35945203, 2022). "It was found that upregulation of FABP4 suppressed GC cell metastasis (mice with FABP4-overexpressing tumours showed significantly lower number of metastatic colonies in the lungs than mice with tumours that did not overexpress) FABP4, while downregulation of FABP4 expression increased metastasis." (PMID 35198079, 2022). "FABP4 inhibited GC metastasis but did not influence tumour growth in vitro and in vivo." (PMID 35198079, 2022). "However, the potential function of FABP4 in COAD and whether it is related to tumor immune infiltrates remain unclear." (PMID 36264920, 2022). "In our tumor model, we found that taxifolin treatment led to reduced expression of genes encoding fatty acid synthesis-related proteins C/EBPa, PPARγ, FABP4, and FAS, suggesting that tumor cell lipid synthesis was reduced and that this may have contributed to the inhibition of tumor growth." (PMID 34462635, 2021). "In vitro experiments also confirmed that the inhibition of these signaling molecules could effectively reduce the tumor spheroid formation, indicating that the activation of the LPL/FABP4/CPT1 axis in the NASH stage may be beneficial to the viability of TICs in liver tissue." (PMID 34803493, 2021). "Furthermore, FABP4 up-regulation induces IL-6/STAT3-mediated DNMT1 overexpression and the silencing of the p15INK4B tumor-suppressor gene in AML cells, thus confirming that FABP4 disruption may be a viable therapeutic strategy." (PMID 31192118, 2019). "According to our proteomics data, FABP4 appears to be overexpressed in the tumor in comparison to the nonneoplastic tissue, and at the same time displayed an uneven distribution across sectors in two of the analyzed specimens (up to 9-fold in one of the tumors)." (PMID 29363612, 2018). "In the present study, both in vitro and in vivo data clearly showed that the adipocyte-derived FABP4 mediates the adipose-induced intracellular lipid accumulation, invasion, migration, and EMT in CCA cells, at least by acting as FA transporter between adipocytes and tumor cells." (PMID 29237483, 2017). "We utilized our invasion system to inhibit the lipid transporter FABP4, and the main adipocyte lipase ATGL and revealed that ATGL-driven lipolysis and FABP4-driven lipid transport might be important for tumor cell–adipocyte interaction in the bone marrow microenvironment." (PMID 27458427, 2016).